IDO1 (indoleamine 2,3-dioxygenase 1)
Diseases named in the same sentence as IDO1 in open-access papers (continued):
Sharing a sentence is not in itself a finding about the gene and the disease.
tumor (continued). "The strong positive correlation of SNRPA1, TMED10, and PROM2 with suppressive immune regulators like IDO1 and VTCN1, and negative correlation with Th1 and MAIT cell infiltration, suggest that these genes may contribute to an immune-evasive tumor microenvironment." (PMID 40826138, 2025). "IDO1 overexpression leads to Trp depletion, which in turn leads to inhibition of the mammalian target of rapamycin complex (mTORC) pathway and activation of the stress-response general control over nonderepressible (GCN2) kinase in tumor-infiltrating T cells, which both lead to immunosuppression." (PMID 38736462, 2024). "However, there are no reports that immune checkpoint IDO1 may shape the cancer immune landscape in the TME and promote tumor progression by interaction with the OS-derived exosome miRNAs." (PMID 37284323, 2023). "Therefore, tumor cells might abnormally amplify the negative feedback regulatory mechanism of IDO1-AhR-STING, which inhibits immune overactivation under physiological conditions, resulting in tumor immune escape." (PMID 37670034, 2023). "First, Trp depletion induced by IDO1 in the TME suppress the mammalian target of rapamycin complex (mTORC) pathway and activates the stress response kinase general control over nonderepressible 2 (GCN2) in tumor-infiltrating T cells, leading to their anergy and apoptosis." (PMID 35173722, 2022). "Moreover, almost all tumors expressing PD-L1 coexpress IDO (not specified if IDO1 or IDO2 as well), but more than half of tumor-expressing IDO lacks PD-L1 expression, suggesting that IDO-expressing tumors are significantly more common than PD-L1–expressing ones." (PMID 36119020, 2022). "Our finding that IDO1 immunoreactivity was confined to tumor blood vessels (and not in adjacent normal kidney vessels), suggests that RCC tumors are using the well-described immunosuppressive mechanism of intra-tumoral activation of IDO1 expression and enhancement of the local kynurenine pathway." (PMID 27572319, 2016). "Using the IDO1 inhibitor GDC-0919, we demonstrate that although a reduction is Kyn is observed, it is not complete, which may be attributed to parallel pathways a tumor may utilize to generate this metabolite independent of IDO1 or incomplete enzyme inhibition by this compound." (PMID 36927729, 2023). "However one study found that IDO1 expression in the tumor microenvironment and normal tissue in NSCLC was not significantly different, which may be one of the reasons for the lack of clinical benefit of IDO1 inhibitors." (PMID 37795038, 2023). "In the supernatant from wt control HeLa cells, we could not detect any tryptophan after 24 hr of IDO1 induction as expected; by contrast, in the same samples, we detected 45 ± 2 μM of KYN; this concentration is consistent with previous observation of KYN concentrations at ~37 μM in a tumor model." (PMID 35245456, 2022). "However, Ido1+ tumors grow faster than Ido1− tumors in immunodeficient SCID/beige mice (lacking T, B, and NK cells) suggesting that some Ido1-controlled nonimmunological mechanisms may be involved in tumor cell growth regulation." (PMID 22654951, 2012).
cancer (984 papers, 2006 to 2026). A tumor composed of atypical neoplastic, often pleomorphic cells that invade other tissues. "Indoleamine 2,3-dioxygenase 1 (IDO1) is a heme-containing enzyme implicated in cancer immune escape and remains an attractive therapeutic target despite recent clinical setbacks." (PMID 42210816, 2026). "We have recently shown that TYK2 suppresses the expression of indolamine 2-3-deoxygenase 1 (Ido-1) in cancer cells, thereby promoting anti-cancer immunity of autochthonous colitis-associated CRC." (PMID 40991399, 2026). "Preclinical studies have demonstrated that inhibiting these proteins can make cancer cells more susceptible to chemotherapy, modulate the immune response by affecting PD-L1 and IDO1 expression, and induce direct cytotoxic effects." (PMID 41148842, 2025). "Production of these tryptophan metabolites is dependent, to a large extent, on proximal tryptophan dioxygenases, including IDO1, which itself is associated with cancer immunosuppression and has been targeted for cancer immunotherapy." (PMID 40449595, 2025). "Indoleamine 2,3-dioxygenase 1 gene (IDO1) is upregulated in many types of cancers and associated with a poor prognosis, contributing to an immunosuppressive TME." (PMID 40848064, 2025). "Raised IDO1 levels have been implicated in reduced survival rates in cancers, such as uterine corpus endometrial carcinoma." (PMID 41332472, 2025). "Although in most studies IDO-1 expression has been associated with a worse outcome in several cancer types, some studies also reported positive prognostic effects." (PMID 40475772, 2025). "In HPV-associated cancers, tumors can adapt to primary checkpoint blockade by upregulating alternative pathways, with IDO1 frequently elevated in HPV-positive tumors, leading to T cell suppression and immune tolerance." (PMID 40282436, 2025). "The overexpression of IDO1 in TCs has been associated with poor survival outcomes in a variety of cancers, including PDAC." (PMID 40075563, 2025). "Certain conditions, such as inflammation, cancer, kidney dysfunction, pregnancy, and treatments like interferon therapy or indoleamine 2,3-dioxygenase 1 (IDO1) inhibitors, are associated with altered tryptophan metabolism." (PMID 40694567, 2025). "Elevated expression of indoleamine 2,3-dioxygenase 1 (IDO1) in cancer cells causes local tryptophan starvation and kynurenine production, inhibiting effector T cells and natural killer cells." (PMID 39962447, 2025). "In HPV-associated cancers, such as cervical cancer, IDO1 expression is upregulated and correlates with HPV antigen expression." (PMID 40282436, 2025). "Many human cancers, including BC, express IDO1, and its upregulated expression has been linked to an unfavorable prognosis." (PMID 39371092, 2024). "We sought to elucidate the connection between IDO1 expression and immune infiltration since TIICs have been linked to the prognosis and treatment of many forms of cancer." (PMID 38539263, 2024). "The role of IDO1 in both cancer and organ transplantation appears to be linked to its immunomodulatory functions." (PMID 39064305, 2024). "The IDO1 gene can be induced by interferon and is associated with mediating potent immunosuppressive effects in cancer." (PMID 38539263, 2024). "IDO1 has been linked to mediating strong immunosuppressive effects in cancer and is interferon-inducible." (PMID 38539263, 2024). "IDO1 expression and clinical outcomes have shown strong associations in a variety of cancers, including BC." (PMID 39371092, 2024). "In the current investigation, we discovered that the levels of different TIICs, such as B cells, phagocytes, CD8T cells, CD4T cells, bone marrow dendritic cells, and NK cells, were closely linked with the levels of IDO1 expression in different cancers." (PMID 38539263, 2024). "This correlation is mainly returned to the fact that IDO1 is positively correlated with the presence of cancer-associated inflammation." (PMID 38736462, 2024).
cancer (continued). "Preclinical and clinical studies support that IDO-1 overexpression is associated with a poor prognosis across a spectrum of pathologies and is best demonstrated in cancer." (PMID 37371332, 2023). "IDO1 is an enzyme that is overexpressed in many cancer cells and is associated with immunosuppression." (PMID 37766359, 2023). "IDO1, which is highly expressed in tumors and associated with resistance to ICBs, has been considered as a promising target for cancer therapy." (PMID 37655051, 2023). "Some studies have demonstrated that IDO1 was associated with potently regulating immunosuppressive effects in cancer." (PMID 35359374, 2022). "IDO1 has been implicated in mediating immunosuppression in cancer, and high expression of IDO1 in CRC cells can counteract T cell invasion through tryptophan depletion and production of proapoptotic tryptophan catabolites." (PMID 36248886, 2022). "In the systematic review, we would analyze the association of IDO1 expression in treatment-naive tissue with cancer survival." (PMID 36212460, 2022). "Nevertheless, AhR activation is not the only factor that is believed to underlie the failure of IDO1 inhibitors in cancer treatment." (PMID 36163134, 2022). "IDO1 is a target for cancer immunotherapy and encodes a heme enzyme that acts on multiple tryptophan substrates and plays a crucial role in pathophysiological processes such as immunoregulation, antitumor defense, and antioxidant activity." (PMID 35654793, 2022). "Recent improvements in understanding the immunological changes caused by chemotherapy and advances in combining checkpoint IDO1 inhibitors with conventional chemotherapy are promising for increasing numbers of cancer." (PMID 35918736, 2022). "IDO1 expression in cancer tissue has been linked to the progression of different types of GC and can predict overall survival." (PMID 34203517, 2021). "Among these, IDO1 is highly expressed in most types of cancer and is associated with the poor prognosis of patients." (PMID 33934540, 2021). "Indoleamine 2,3-dioxygenase 1 (IDO1) is an enzyme of tryptophan metabolism, and it is associated with poor prognosis by enabling malignant tumors to avoid immune surveillance." (PMID 34285260, 2021). "Studies have shown that relative to IDO2 and TDO, IDO1 has lower substrate specificity to catabolize Trp, and is associated with poor survival of various cancer patients." (PMID 33883013, 2021). "A recent analysis of the Cancer Genome Atlas (TCGA) database indicated that T cell infiltration was more associated with IDO1 than PD-L1, and EBV-associated cancers were correlated with IDO1." (PMID 34944437, 2021). "Another meta-analysis showed a similar result: increased IDO1 expression was significantly associated with reduced OS in many types of cancer (HR 1.92, 95% CI = 1.52–2.43, p < 0.001)." (PMID 34943606, 2021). "Preclinical studies also support that IDO1 overexpression is associated with poor prognosis in the majority of cancers." (PMID 33883013, 2021). "High levels of IDO1 have been found in several tumors in association with cancer progression and poor prognosis." (PMID 34445444, 2021). "Aiming at the cancer-associated events triggered by IDO1 pathways, most researchers focused on the enzymatic effects of IDO1." (PMID 34539663, 2021). "Although less studied, polymorphisms in IDO1 have been reported to be associated with overall survival in early stage cancer." (PMID 34557196, 2021). "Among all the significant associations, CD36 expression was negatively correlated with ADORA2A and LAG3 in multiple cancer types, but positively associated with IDO1, IDO2, and KIR3DL1 in multiple cancers." (PMID 34234847, 2021). "Kyn activates the AhR-ARNT associated transcription of IL-6 in human cancer cell lines, provoking autocrine activation of IDO1 via STAT3." (PMID 32957545, 2020).
cancer (continued). "Epacadostat is an inhibitor of indoleamine 2,3-dioxygenase-1 (IDO1) that showed antitumor activity in several cancer models, especially when associated with other immunotherapy agents." (PMID 33375286, 2020). "Since some of these genes encode metabolic enzymes, IFN-γ exposure alters cancer metabolism; for example, indoleamine 2,3-dioxygenase 1 (IDO1) induced by IFN-γ is the rate-limiting enzyme of tryptophan catabolism via the kynurenine pathway." (PMID 32275689, 2020). "IDO1 was found to be overexpressed in certain types of cancer and causes immune escape and metastasis, resulting in poor prognosis of patients." (PMID 32545442, 2020). "Increased expression of IDO1 in cancer was associated with immune escape and cancer-associated inflammation in the microenvironment." (PMID 32824193, 2020). "The obtained DOX/aNLG919-loaded CaCO3 nanoparticles (DNCaNPs) are able to cause effective ICD of cancer cells and at the same time restrict the production of immunosuppressive kynurenine by inhibiting IDO1." (PMID 34138248, 2020). "IFN-γ induces expression of genes encoding IDO1 and PD-L1, which are associated with cancer cell immune evasion." (PMID 32275689, 2020). "IDO-1 is suggested as such a diagnostic marker of cancer therapy, especially since the tryptophan metabolic pathway is considered as a regulator of innate and adaptive immunity and has the ability to suppress T cell responses." (PMID 32384638, 2020). "The finding that high IDO1 expression is associated with shorter survival in cancer patients made IDO1 a promising target either by specific inhibitors or indirectly by immunomodulation." (PMID 32117235, 2020). "Because IDO1 is overexpressed in several types of cancer, it has been strongly linked to cancer immunoediting." (PMID 32907554, 2020). "Among KP metabolites, KYN production has been linked to cancer immune escape and is primarily explained by the role played by IDO1 inhibition which has emerged as a potential candidate in the context of cancer immune therapy." (PMID 31434983, 2019). "It has been shown that cancer increases the consumption of tryptophan to evade immune control and this has been linked to IDO1 activity." (PMID 31842810, 2019). "IDO1 activity is upregulated in many types of human cancer and tends to be associated with a poor prognosis." (PMID 31383907, 2019). "Preclinical genetic proofs of IDO1 as a valid therapeutic target in cancer were enabled in IDO1-deficient mice, where fundamental connections between IDO1 expression and cancerous inflammatory programs were also established." (PMID 30254983, 2018). "Cancer-associated fibroblasts recruit and educate DCs to become IDO1-producing regulatory DCs through IL-6-mediated STAT3 activation." (PMID 30068361, 2018). "IDO1 has been shown to be active in many human cancers and its expression has been associated widely with poor prognosis." (PMID 30254983, 2018). "A causal relationship between IDO1 activity and cancer growth was founded by pivotal studies in the 2000s that have been reviewed in detail elsewhere." (PMID 30254983, 2018). "Navoximod (GDC-0919; previously NLG919) is an investigational small molecule inhibitor of IDO1 that was developed to treat the immune tolerance associated with cancer." (PMID 29921320, 2018). "Indoleamine 2,3-dioxygenase 1 (IDO1), an enzyme able to degrade tryptophan into kynurenine, is a nodal mediator of pathogenic inflammation and immune escape in cancer." (PMID 25886742, 2015). "In the past years, it has become increasingly clear that IDO1 is part of an oncogenic signature in cancer supporting the concept that cell-autonomous pathways driving cancer cells are intricately linked to an immunosuppressive phenotype." (PMID 25628622, 2014). "Comparing levels of IDO1 mRNA within the TCGA data set (n = 748) revealed a significant positive correlation of IDO1 mRNA levels with vimentin expression (a hallmark of basal cancers)." (PMID 25091696, 2014).
cancer (continued). "IDO1 functions to cause local tryptophan depletion under physiological and pathogenic immune tolerance settings such as during placentation and cancer where it is considered to be critical for establishing local immune tolerance." (PMID 23671415, 2013). "One mechanism of immune escape that has been linked to cancer is elevation of the tryptophan-catabolizing enzyme, indoleamine 2,3-dioxygenase (IDO1)." (PMID 22654951, 2012). "IDO1/TDO2 are upregulated in various cancers and associated with poor prognosis." (PMID 41293169, 2025). "IDO-1 expression and activity has been reported in several human cancers, but there is a strong contradiction in the literature about its prognostic role; although in most studies IDO-1 expression has been associated with worse outcomes, some studies also reported a positive prognostic effect." (PMID 40475772, 2025). "IDO1 regulates tryptophan metabolism by catabolizing tryptophan to kynurenine, and reduced tryptophan levels are associated with poor outcomes among multiple cancer types 58-60." (PMID 39239507, 2024). "IDO1 is overexpressed in various forms of cancer and is linked to a bad prognosis." (PMID 38539263, 2024). "Overexpression of IDO1 is associated with poor prognosis in various cancers." (PMID 39064305, 2024). "Then, we plotted the ROC curve of the IDO1 gene and associated cancers." (PMID 38539263, 2024). "Further, the abnormally high IDO1 expression in cancer cells, associated with tryptophan metabolic reprogramming, could contribute to L-kyn changes in EVs, resulting in increased L-kyn levels in EVs obtained from plasma and the TME in OC patients." (PMID 38468343, 2024). "Kyn-pathway controlled IDO1 has been associated with poor prognosis in various cancers." (PMID 36879122, 2023). "High IDO1 expression was associated with poor prognosis in a range of cancers." (PMID 36798123, 2023). "Indeed, IDO1 expression correlates with the enhanced aggressiveness of cancer cells via the dysregulation of the markers linked with epithelial-to-mesenchymal transition such as E-cadherin, N-cadherin, and vimentin." (PMID 38201550, 2023). "Except for BAI1, CD31, and MerTK, the enhanced expression of Axl, Tyro3, Gas6, MFGE8, Stab2, Tim-4, CX3CL1, IDO1, Rac1, and PD-L1 was associated with decreased sensitivity to many drugs, which may partially explain the resistance to chemotherapy in cancers." (PMID 36059952, 2022). "So the accumulation of immunosuppressive cells and increased levels of immunosuppressive molecules such as PD-1 ligand (PD-L1) and indoleamine 2,3-dioxygenase 1 (IDO1) are directly associated with poor prognosis and unfavorable disease outcomes in patients with cancer." (PMID 36003765, 2022). "IDO1 overexpression has been associated with cancer progression in an increasing number of studies." (PMID 36139584, 2022). "IDO1 activity has been associated with many diseases including hepatitis B infection, malaria, psychiatric disorders, atherosclerosis as well as cancer and the immune escape often observed in tumors." (PMID 36386899, 2022). "Overexpression of IDO1/TDO2 is also associated with poor prognosis in various cancers." (PMID 35406118, 2022). "High expression of IDO1 was associated with poor clinical outcomes, indicating that it could be a potential prognostic marker in various cancer types." (PMID 36212460, 2022). "High IDO1 levels are associated with poor prognosis in several cancer types." (PMID 34203535, 2021). "In addition, we recently identified the L-amino acid oxidase interleukin-4-induced-1 (IL4I1) as a novel and very potent upstream regulator of AHR, and we showed that IL4I1 associates more frequently with AHR activity than IDO1 or TDO2 in cancer." (PMID 33920868, 2021). "Finally, given the potential of nanotechnology, we foresee an ever-rising use of nanomaterials for providing accurate delivery of treatments targeting IDO1-associated dormancy and enhancing cancer therapy." (PMID 34539663, 2021).